TSLP (thymic stromal lymphopoietin)
Diseases named in the same sentence as TSLP in open-access papers (continued):
Sharing a sentence is not in itself a finding about the gene and the disease.
asthma (continued). "It has been found that MC infiltrating to the mucosal gland stroma and airway smooth muscle in asthma not only express high levels of TSLP mRNA, but can also respond to TSLP." (PMID 22876248, 2012). "TSLP levels are increased in human asthma and correlate with the increase in expression of Th2 cytokines and disease severity." (PMID 22876248, 2012). "Mice expressing TSLP in the lungs spontaneously develop an airway inflammatory disorder with characteristics similar to those of human asthma." (PMID 22523502, 2012). "TSLP is an important factor in the pathogenesis of asthma and a potential therapeutic target for the treatment of allergic diseases." (PMID 23194010, 2012). "Blocking of TSLP signaling using TSLPR-immunoglobulin in murine asthma model, was shown to regulate pulmonary DC function and to reduce eosinophilic airway inflammation and Th2 differentiation significantly." (PMID 22876248, 2012). "Different studies have shown that asthma, allergic rhinitis, and atopic dermatitis are characterized by an increased expression of TSLP in the inflamed tissue." (PMID 22876248, 2012). "Airway epithelial cell expression of TSLP is both necessary and sufficient for the development of airway inflammation in murine models of antigen-induced asthma." (PMID 21966427, 2011). "In this study, we report an analysis of association between single nucleotide polymorphisms (SNPs) in TSLP, OX40L, IL7R, and RXRα and AR in three independent studies of children with asthma from Costa Rica, North America, and Sweden." (PMID 21244681, 2011). "Our work highlights that TSLP likely plays a role in the pathogenesis of AR in children with asthma." (PMID 21244681, 2011). "If indeed serum TSLP levels are elevated in AD patients, our findings suggest that an aggressive management of TSLP levels in these patients will lower the incidence of asthma later in their lives." (PMID 19557146, 2009). "TSLP expression is increased in asthmatic airways and correlates with both the expression of Th2-attracting chemokines and with disease severity, indicating a link between TSLP and human asthma." (PMID 18724870, 2008). "In patients with asthma who have a pre-existing tendency toward allergic (Th2-skewed) inflammation, the presence of Th2 cytokines—particularly IL-4 and IL-13—amplifies the release of TSLP and IL-8 from small airway epithelial cells." (PMID 41576028, 2026). "In addition to treating severe asthma, ecleralimab, a newly developed inhaled anti‐TSLP biologic, holds potential for application in patients with mild atopic asthma." (PMID 41568067, 2026). "Since both IL-4 and IL-13 contribute to a positive feedback loop that promotes TSLP expression, inhibition of their signaling by dupilumab may help mitigate inflammation during virus-induced asthma exacerbations by indirectly reducing TSLP production." (PMID 41576028, 2026). "The anti‐TSLP monoclonal antibody tezepelumab has demonstrated remarkable efficacy in Phase I and II clinical trials, exhibiting improvements in pulmonary function, reduction of eosinophils, and alleviation of asthma symptoms." (PMID 41568067, 2026). "Ecleralimab is an anti-TSLP IgG1λ Fab that was in development for asthma." (PMID 41409758, 2025). "Type‐2 (T2) inflammation plays a key role in both asthma and atopic dermatitis, and key T2 cytokines such as interleukins (IL) 4, 5, and 13, and epithelial alarmins such as thymic stromal lymphopoietin (TSLP) and IL33 drive inflammation." (PMID 40662227, 2025). "Notably, research has demonstrated that allergic rhinitis (AR) and other atopic conditions share Th2 inflammatory pathways with asthma, indicating that TSLP can be induced by nasal epithelial stimulation upon allergen exposure." (PMID 40503233, 2025). "TSLP is released as a result of epithelial injury and inflammation of the bronchial epithelium and thereby becomes central to the pathogenesis of Type 2 (T2) inflammation in asthma." (PMID 40283665, 2025).
asthma (continued). "Therefore, we conclude in this study the TRPA1 is the primary mediator of TSLP induction in response to cold exposure, potentially contributing to asthma exacerbations." (PMID 41322401, 2025). "Short and long isoforms of the cytokine may explain the paradoxical activities of TSLP, as the long isoform is elevated in a variety of inflammatory diseases, including asthma, ulcerative colitis, and Celiac disease." (PMID 40426880, 2025). "In AD and asthma, TSLP is highly expressed in the epithelium of the skin and lungs, respectively." (PMID 39962262, 2025). "This overexpression of TSLP in asthma BECs may play a critical role in asthma exacerbations, as TSLP is a key cytokine that amplifies T2 immune responses and promotes airway inflammation." (PMID 40370530, 2025). "An ultrasensitive immunosensor for asthma biomarker thymic stromal lymphopoietin (TSLP) by integrating a dual-luminescent T-COF constructed from AIE-active monomer and 9,10-anthracenedicarboxaldehyde units into a microfluidic chip and pairing it with camel-derived nanobodies." (PMID 41294770, 2025). "The results indicated that keratinocytic TSLP may act as an important mediator in the link of AD to asthma." (PMID 40236701, 2025). "Scientists have been trying to define the role of TSLP in the pathogenesis of asthma." (PMID 40723867, 2025). "Moreover, TSLP expression was elevated in the smooth muscle of the airway and lungs in patients with mild-to-moderate and severe asthma." (PMID 39940994, 2025). "Tezepelumab is an anti‐TSLP monoclonal antibody approved for the treatment of severe asthma." (PMID 40365686, 2025). "This discrepancy may be attributed to differences in sample type, study population characteristics, and methodological approaches, highlighting the need for further validation of TSLP as a prognostic biomarker for asthma remission across diverse cohorts." (PMID 40503233, 2025). "Additionally, comorbid allergic conditions likely contributed to elevated baseline TSLP levels further complicating its role as an asthma-specific biomarker." (PMID 40503233, 2025). "TAVO101 is a humanized anti-TSLP monoclonal antibody modified for extended half-life (LS mutation) in phase 2 development for atopic dermatitis (NCT06176040) and plans for development in asthma, COPD, and rhinitis." (PMID 41409758, 2025). "Biologic therapies target type 2 inflammatory mediators, such as immunoglobulin E (IgE), interleukin-4 (IL-4) and interleukin-5 (IL-5), and thymic stromal lymphopoietin (TSLP), thereby reducing asthma exacerbations and OCS use while improving QOL and lung function." (PMID 40861628, 2025). "Furthermore, our sub-analysis revealed that TSLP+ cells were higher in severe and EXA MIXED groups than mild and NON-EXA MIXED, suggesting the connection of this alarmin with asthma severity, also due to the strong correlation of TSLP with ICS dose." (PMID 40022191, 2025). "TAVO101 was a highly effective TSLP neutralizer and showed promising pharmacokinetic profiles in preclinical models, suggesting that it represents a promising candidate in the therapeutic arsenal for the treatment of asthma and other inflammatory diseases." (PMID 40283665, 2025). "When various biological agents relate to IgE, thymic stromal lymphopoietin (TSLP) and Th2 cytokines (IL-4, IL-5, IL-13) are added to intensive controller medications; these agents are somewhat effective for a subgroup of patients with severe asthma." (PMID 40001485, 2025). "In virus-induced asthma, the role of TSLP is particularly important." (PMID 40636260, 2025). "Future studies are needed to understand the role of TSLP in T2low asthma." (PMID 41145900, 2025). "Airway TSLP expression correlates with asthma severity and bronchial obstruction." (PMID 41321706, 2025). "IL-25, IL-33 and TSLP are also epithelial-derived cytokine that are important in the pathogenesis of CRSwNP and asthma, and may be potential relevant biomarkers for CRSwNP." (PMID 40469214, 2025).
asthma (continued). "In patients diagnosed with asthma and nasal polyps (NPs), TSLP activates fibroblasts and smooth muscle cells in conjunction with other cytokines, such as IL-1, IL-6, and TNF-alpha, to induce smooth muscle hypertrophy and increased remodeling of the bronchial and nasal epithelium." (PMID 39940994, 2025). "In vivo studies using tezepelumab to inhibit TSLP in asthma patients showed a decrease in the airway epithelial inflammatory response, including reductions in IL-33 and type 2 cytokines when faced with a viral challenge, all while preserving the body’s natural resistance to viruses." (PMID 40303400, 2025). "The current biologics for severe asthma treatment include omalizumab (anti-IgE), mepolizumab and reslizumab (anti-IL-5), benralizumab (anti-IL-5 receptor), dupilumab (anti-IL-4/IL-13), and tezepelumab (anti-TSLP)." (PMID 40364184, 2025). "Thus, prolonged treatment with a combination of IL-4 and IL-13 downregulated TSLP secretion and IFNλ1 gene expression, while inducing IFNβ expression, especially in BECs from asthma patients." (PMID 40370530, 2025). "Additionally, mouse models across asthma stages were established to measure TSLP levels in BALF, serum, and lung tissue, to validate its predictor value." (PMID 40503233, 2025). "Approved asthma biologic antibodies target critical points surrounding the T2 immune response including T2 cytokine signaling (IL-4, IL-5, and IL-13), downstream T2 response (IgE), and upstream T2 initiation [thymic stromal lymphopoietin (TSLP)]." (PMID 39586024, 2025). "This is exemplified by the low-scoring Europe PMC’s pieces of evidence for the TSLP and asthma association between 2012 and 2014, and the corresponding novelty peaks." (PMID 41354649, 2025). "As a potent activator of ILC2s, TSLP is a key molecule in the progression of AD to asthma." (PMID 40236701, 2025). "TSLP acts as an alarmin following perturbation of the airway epithelium and has been identified to play a role in the pathogenesis of asthma through its effects on a wide range of effector cells of the innate and adaptive immune response and activation of multiple downstream inflammatory pathways." (PMID 40365686, 2025). "TSLP released from sources other than the lungs—such as adipose tissue—might potentially affect airway inflammation and influence asthma severity, partially explaining higher blood TSLP concentrations in patients with higher BMI." (PMID 41357156, 2025). "Despite the key role of TSLP in early asthma mouse modelling, TSLP cellular sources during challenges to the lung are not well characterised, although one study has documented TSLP production by lung adventitial stromal cells, capable of supporting ILC2 responses." (PMID 40944312, 2025). "This suggests that TSLP could serve as an indicator in biomarker level to predict remission in pediatric Th2-high asthma." (PMID 40503233, 2025). "TSLP is certainly one of the most promising targets for treating T2low asthma." (PMID 41145900, 2025). "Further research is needed to clarify this relationship and determine whether serum TSLP can serve as a reliable marker for airway inflammation in asthma." (PMID 41357156, 2025). "This umbrella review indicated that anti-IgE treatment, anti-IL5/5Rα treatment, anti-IL4Rα treatment, and anti-TSLP treatment may be beneficial to patients with severe asthma." (PMID 40520782, 2025). "Filaggrin deficiency, known in AD, may also promote Th2 inflammation in airways by affecting E‐cadherin expression and enhancing IL‐33/TSLP release, potentially contributing to asthma." (PMID 40679787, 2025). "Early genomic studies indicated that polymorphism in several genes related to PRRs, such as TLRs or NODs, is related to asthma, while a larger genome-wide association study (GWAS) additionally identified IL-33, ST2, and TSLP (thymic stromal lymphoprotein) as being important in asthma." (PMID 39861052, 2025).
asthma (continued). "It remains to be seen whether all the beneficial effects of tezepelumab, including those on mucus plugs, persist after biological cessation, making this TSLP-targeting antibody a true disease-modifying drug in asthma." (PMID 41145900, 2025). "In recent years, the role of ILC2 in the pathogenesis of T2 asthma has been clarified with evidence of the triggering effect of thymic stromal lymphopoietin (TSLP) and IL-33, which have been correlated with more severe asthma, as well as glucocorticoid resistance." (PMID 40364184, 2025). "Serum TSLP was the only biomarker that exhibited a statistically significant increase in acute exacerbation and persistent asthma compared to remission and control groups (P<0.01), highlighting its potential prognostic value in pediatric Th2-high asthma." (PMID 40503233, 2025). "A significant increase in the infiltration of inflammatory cells and eosinophils around blood vessels and bronchioles was observed in the lungs of group B mice relative to the control group A, indicating the establishment of asthma-related lesions by TSLP/OVA administration." (PMID 41294800, 2025). "Indeed, PF-07275315, a trispecific antibody targeting TSLP, IL-4 and IL-13 simultaneously, is being evaluated in Phase II trials for asthma and atopic dermatitis." (PMID 41294800, 2025). "Except for tezepelumab (anti-TSLP), these biologics are approved for asthma with specific biomarker elevations relevant to these pathways: sensitization to a perennial aeroallergen (anti-IgE), elevated AEC [anti-IL-5, anti-IL-5 receptor (IL-5R), anti-IL-4Rα], and increased FeNO (anti-IL-4Rα)." (PMID 39586024, 2025). "To date, clinical data concerning asthma are available for only one anti-TSLP therapy, tezepelumab." (PMID 41145900, 2025). "TSLP in sputum was associated with the degree of AHR in patients with asthma irrespective of eosinophil levels supporting the role of AHR." (PMID 40303400, 2025). "The study conducted on people whose omentin expression in lungs was suppressed using nonsense mRNA showed that the synthesis of IL-25, IL-33, and TSLP was consequently decreased, directly linking omentin’s role in their production and, therefore, in the asthma development." (PMID 40149608, 2025). "Furthermore, IFN-λ can limit the decrease TSLP and IL-33 production, providing evidence for a protective role in asthma exacerbations." (PMID 40636260, 2025). "This study also ignited interest in TSLP's role in asthma, noting TSLP overexpression in lung epithelial cells to induce an asthmatic phenotype, resulting eventually in the development of Tezepelumab for treatment of human asthma." (PMID 40944312, 2025). "If confirmed, the role of TSLP in GERD could support its use as a diagnostic biomarker and as a therapeutic target, as has been proposed in asthma." (PMID 40981017, 2025). "The validity of measuring systemic or local expression of TSLP in the diagnosis or in the management of asthma remains unclear." (PMID 41357156, 2025). "Furthermore, multiple genes, such as ATF3, activation‐induced cytidine deaminase (AICDA), thymic stromal lymphopoietin (TSLP), and endothelin receptor type A (EDNRA), are associated with asthma." (PMID 37385291, 2025). "In recent years, some research hot words such as “severe asthma,” “innate lymphoid cells,” “thymic stromal lymphopoietin,” “NF-κB,” “airway remodeling” and “NLRP3 inflammasome” have emerged, and a large number of articles have conducted in-depth research on them." (PMID 39029036, 2024). "A study using a murine model showed that induction of systemic release of TSLP could drive the development of an asthmatic phenotype after antigen challenge in the lungs, and blockade of TSLP signaling rescued the development of asthma." (PMID 38566968, 2024). "Indeed, initial clinical trials targeting IL-33 using Itepekimab or TSLP through the application of Tezepelumab show promising clinical results by reducing asthma symptoms." (PMID 39497825, 2024).
asthma (continued). "Thymic stromal lymphopoietin (TSLP) is an epithelial-derived pleiotropic cytokine that regulates T-helper 2 (Th2) immune responses in the lung and plays a major role in severe uncontrolled asthma." (PMID 38469627, 2024). "However, alarmins, including IL-25, IL-33, and TSLP, derived from airway epithelial cells, have received increasing focus as upstream targets to block initial type 2 reactions and improve asthma control." (PMID 39200943, 2024). "In response to viral or fungal stimuli, airway epithelial cells from individuals with asthma release even greater amounts of TSLP, thereby polarizing T helper 2 (Th2) cells and expanding innate lymphoid (ILC2) cells to enhance the production of T2 cytokines, including IL-4, IL-13, and IL-5." (PMID 38672419, 2024). "Biologics targeting IgE, IL-5, IL-4/IL-13, and TSLP are crucial in severe asthma treatment." (PMID 38525773, 2024). "At the cellular level, TSLP/OVA induced asthma was accompanied with a significant infiltration of CD45+ leukocytes and eosinophils which are crucial in allergic responses during asthma pathogenesis, but not neutrophils or macrophages, in the BALF of asthmatic mice." (PMID 39726595, 2024). "T2 asthma is triggered by allergens, pollutants, and microorganisms that are captured by dendritic cells leading to the release of interleukin (IL)-25, IL-33, and thymic stromal lymphopoietin (TSLP) from bronchial epithelial cells." (PMID 39064286, 2024). "It is commonly known that TSLP and other cytokines generated from epithelial cells, IL-25, and IL-33 are essential in the development of allergic disorders, such as food hypersensitivity, asthma, and AD." (PMID 39057040, 2024). "The influence of the genetic association of the polymorphism on the role of the TSLP gene in asthma is not clear." (PMID 39118763, 2024). "Furthermore, TSLP blockade suppressed airway remodelling in a mouse model of asthma via reduced MMP, TGF-β and connective tissue growth factor levels." (PMID 38609094, 2024). "Tezepelumab, an anti-TSLP mAb, has been shown to be safe, well tolerated, and effective in improving asthma control, also reducing the incidence of exacerbation and hospitalization in patients with severe asthma." (PMID 39598410, 2024). "However, recently, owing these properties of TSLP, FDA has approved anti-TSLP tezepelumab as an add-on maintenance therapy to improve severe asthma to those uncontrolled on regular therapy." (PMID 39118763, 2024). "al studied plasma TSLP levels in association with asthma characteristics and their evolution among adults with non-severe asthma in a large epidemiological study." (PMID 38731070, 2024). "Currently, there are several anti-TSLP monoclonal antibodies under development, in which tezepelumab demonstrated positive results in treating patients with poorly controlled severe asthma in the phase 3 clinical trial." (PMID 39076593, 2024). "The immunopathophysiology of allergic conjunctivitis is similar to that of asthma and allergic rhinitis because Th2-derived cytokines, Th9-derived cytokine, IL-33, and TSLP induce the type 2 allergic immune-mediated inflammatory processes in these allergic diseases." (PMID 38541674, 2024). "In summary, TSLP can induce innate and T2 inflammation simultaneously, thereby increasing tissue mucus, airway remodeling, and severe cell fibrosis, and gradually evolving into asthma." (PMID 39076593, 2024). "Other researchers suggest that TSLP levels in sputum may be a more reliable predictor of asthma compared to serum TSLP levels." (PMID 38731070, 2024). "This herb targets the IL-33/TSLP signaling pathway and significantly lowers the levels of these cytokines in the nasal and bronchoalveolar lavage fluids of mice modeling allergic rhinitis and asthma." (PMID 38931338, 2024). "The expression of TSLP and, to a lesser extent, IL-25 is increased in patients with severe asthma." (PMID 38999286, 2024).